MCL1 (MCL1 apoptosis regulator, BCL2 family member)
Diseases named in the same sentence as MCL1 in open-access papers (continued):
Sharing a sentence is not in itself a finding about the gene and the disease.
lung carcinoma (continued). "We therefore treated H1299 lung cancer cells with MCL1 inhibitor S6384525 individually or together with Verteporfin that inhibits TAZ function to further validate our interaction result as well as test if there are synergistic inhibition effects in H1299 cell growth." (PMID 31601883, 2019). "In lung cancer, Mcl-1 has been shown to be a promising target of drug action." (PMID 31117253, 2019). "Although the decrease of Mcl-1 and Bcl-2 was notified after treatment with avicequinone B at 1–4 μM, the significantly reduction of caveolin-1 and induction of anoikis were only observed in human lung cancer cells incubated with avicequinone B at 4 μM." (PMID 29631569, 2018). "Moreover, miR-101-3p mimics downregulated MCL1 expression in lung cancer cells, thereby confirming that miR-101-3p negatively regulates MCL1." (PMID 29484127, 2018). "Furthermore, qRT-PCR analysis of lung cancer tissues revealed that MCL-1 expression negatively correlates with miR-101-3p levels (R = -0.556)." (PMID 29484127, 2018). "There was positive correlation between MALAT1 and MCL1 mRNA expression in lung cancer tissues." (PMID 29484127, 2018). "Silencing MCL1 by miR-101-3p mimics enhanced cisplatin cytotoxicity in the lung cancer cells." (PMID 29484127, 2018). "Similarly, it has been shown that knockdown of PTBP1 increases MCL1 mRNA accumulation in the cytoplasm in prostate and lung cancer cells." (PMID 29361709, 2018). "Downregulation of MCL1 increases cisplatin-induced apoptosis in lung cancer cells." (PMID 29484127, 2018). "Interestingly, NOXA and BIM downregulation partially protected H23 lung cancer cells from cell death induced due to MCL-1 knockdown which probably explains why their expression is reduced upon Obatoclax mediated MCL-1 inhibition." (PMID 28947954, 2017). "Moreover, in lung cancer, reduced MCL1 expression sensitized epidermal growth factor receptor mutant non-small cell lung cancers to MEK inhibitors." (PMID 26636651, 2015). "Recently, we have provided the data indicating that Cav-1 in the detached lung cancer cells could inhibit anoikis process of the cells by sustaining the antiapoptotic Mcl-1 protein." (PMID 24967418, 2014). "Our previous studies suggested that HPV may be involved in lung cancer development through up-regulating the expressions of IL-6, IL-17 and the anti-apoptotic Mcl-1, and result in promotion of cancer cell growth." (PMID 23349885, 2013). "In our current study, we further tested the hypothesis that Mcl-1 and Bcl-xL are both overexpressed in colon and lung cancers." (PMID 23171055, 2012). "In cancer, miR-1 induced apoptosis through repression of Mcl-1 in lung cancer." (PMID 21378409, 2011). "Similarly, Mcl‐1 inhibition has been shown to enhance the efficacy of MEKi in lung cancer." (PMID 34861096, 2022). "Furthermore, Mcl-1 is important for the survival of lung cancer cells." (PMID 35447911, 2022). "As with BCL-2 and MCL-1, for which deregulation of the microRNA control of their expression has been described in cancer, miR-133b deregulation has been observed in bladder cancer, colorectal carcinoma and lung cancer leading to BCL-W overexpression in these cancers." (PMID 33799592, 2021). "Furthermore, evaluations involving gastric cancer and lung cancer models could show a direct interaction with MCL1 and BCL proteins." (PMID 34445276, 2021). "Moreover, MCL-1 limits cell death triggered by Cisplatin in lung cancer cells." (PMID 32152280, 2020).
lung carcinoma (continued). "RT, TM-(–)-18, and TM-(–)-4a were the active compounds that were demonstrated to have potent anti-cancer activity in lung cancer cells, and information on the SARs of these compounds could encourage the development of related compounds having these groups for Mcl-1 suppression." (PMID 32260280, 2020). "Nicotine-/NNK-induced phosphorylation of Bcl2 and Mcl-1 enhances their antiapoptotic functions, while phosphorylation of Bax and Bad inactivates their proapoptotic functions, which contributes to increased survival and chemoresistance of human lung cancer cells." (PMID 24967145, 2014). "Thus, disruption of the antiapoptotic function of Mcl-1 by blocking its Thr163 site phosphorylation may represent a new strategy for the treatment of tobacco-related cancer, especially for lung cancer and other malignancies that express Mcl-1." (PMID 24967145, 2014). "B-cell lymphoma 2 (BCL-2) and myeloid cell leukemia 1 (MCL-1), the pro-survival members of BCL-2 family proteins, are upregulated in lung cancer cells and play a critical role in evading apoptosis and drug resistance." (PMID 38666017, 2024). "In lung cancer, the combination of trametinib (MEK inhibitor) and AM-4907 (MCL1 inhibitor) showed tumor regression in xenograft tumors." (PMID 35668118, 2022). "In lung cancer patient samples, high level of BMI1 is correlated with poor survival, and the expression of BMI1 is positively correlated with MCL1." (PMID 35794816, 2022). "In this study, we found that in non‐small cell lung cancer (NSCLC), BMI1 and MCL1 play crucial roles of cancer stemness including invasion, chemo‐resistance and tumour initiation." (PMID 35794816, 2022). "Lung cancer models with stable expression of BCL-xL and MCL-1 treated with radiotherapy induce negligible numbers of apoptotic cells." (PMID 33883020, 2021). "The PEST domain of MCL-1 interacts with AKT on the PH domain to activate AKT, which together promote lung cancer progression." (PMID 33883020, 2021). "Like MCL-1, BCL-XL is one of five genes encompassed in a region of amplification (on 20q11.21) that has been reported in lung cancer, giant-cell tumour of bone and embryonic stem cell lines." (PMID 33799592, 2021). "Next, we examined for changes in the anti-apoptotic Mcl1 protein and induction of PARP cleavage in these lung cancer cells." (PMID 34359807, 2021). "Not only diminution of Mcl-1 and c-FLIP but also up-regulation of Bax, a pro-apoptosis protein, was presented in human lung cancer cells exposed to colicin N." (PMID 32069989, 2020). "Furthermore, DYRK1A mediated proteasome-dependent degradation of Mcl-1 in NSCLC cells, and DYRK1A co-localized with Mcl-1 in NSCLC cells and was co-expressed with Mcl-1 in tumor samples from lung cancer patients, suggesting that Mcl-1 may be a novel DYRK1A substrate." (PMID 32587776, 2020). "MARCH5 depletion also increased basal MCL1 in PC3 PCa cells and in additional prostate, breast and lung cancer cell lines." (PMID 32484436, 2020). "Previous studies in colon cancers, rhabdomyosarcomas, lung cancers, glioblastomas, and ovarian cancers demonstrated that under conditions of cellular duress, including treatment with ABT-263, Mcl-1 protein levels are induced downstream of mTOR signaling." (PMID 31595181, 2019). "Recently, a study in lung cancer cell lines and PDX models showed that combining BGJ398 with either the Bcl‐XL inhibitor A1331852 or the Mcl‐1 inhibitor S63845 led to a small survival benefit and that only triple inhibition resulted in tumour regression." (PMID 30537101, 2019). "In both non–small cell lung cancer (NSCLC) and CRC, Mcl1 accumulation—frequently ascribable to FBXW7-inactivating mutations—leads to intrinsic and acquired resistance to oxaliplatin, 5-FU and several TKIs." (PMID 31569395, 2019). "In lung cancer, miR-133b expression is largely reduced compared to adjacent normal tissues and studies have shown that miR-133b targets the 3′ UTR of both MCL1 and BCLW and promotes gemcitabine-induced apoptosis." (PMID 29361709, 2018).
lung carcinoma (continued). "Specifically, USP13 and MCL1 expression was both observed in 93.3% (28 of 30) of our lung cancer cohort, whereas only 26.7% (8 of 30) and 3.3% (1 of 30) of normal lung tissues displayed positive staining of USP13 and MCL1, respectively." (PMID 29335437, 2018). "Down-regulation of caveolin-1, Mcl-1 and Bcl-2 as well as suppression on AKT and ERK activation successfully initiate detachment-induced cell death in anoikis-resistant lung cancer cells." (PMID 29631569, 2018). "We performed MCL1 knockdown in A549, H1299 and A549/DDP cells to investigate its role in lung cancer." (PMID 29484127, 2018). "Moscatilin, a dibenzyl derivative present in orchid sensitizing anoikis in human lung cancer cells by decreasing the level of Akt and ERK, expression of caveolin 1 and anti apoptotic MCl-1 protein." (PMID 28223935, 2017). "Mcl-1 is an antiapoptotic member of the Bcl-2 family frequently upregulated in NSCLC and promotes lung cancer cell migration." (PMID 27935865, 2017). "MicroRNA-133a, downregulated in osteosarcoma, suppresses proliferation and promotes apoptosis by targeting Bcl-xL and Mcl-1; miRNA-133b targets pro-survival molecules MCL-1 and BCL2L2 in lung cancer." (PMID 32309578, 2016). "To summarize, the apoptosis induced by PTL in lung cancer cells is via both intrinsic and extrinsic apoptotic pathways, the intrinsic apoptosis is mediated through PMAIP1/MCL1 axis." (PMID 24387758, 2014). "miR-29 regulates the anti-apoptotic Bcl-2 family member, Mcl-1 and DNA methyltransferases (DNMT) 3A and 3B and is down-regulated in lung cancer where DNMT is frequently up-regulated." (PMID 23724959, 2013). "miR-133b targets MET in CRC cells; PKM2 in tongue SCC; FSCN1 in ESCC and myeloid cell leukemia sequence 1 (MCL1); and BCL2-like 2 (BCL2L2) in lung cancer." (PMID 22308266, 2012). "Studies in other lung cancer cell lines have also reported additive effects of metformin with DCA under normoxic conditions, suggesting mechanisms related to the inhibition of mTOR1 and MCL-1." (PMID 40507826, 2025). "The increase in the level of MCL1 and BAK mRNA was observed in IBV-infected African green monkey kidney epithelial cells, Vero, and in three other virus-carrying cell lines, i.e., chicken fibroblasts—DF1, lung cancer cells—H1299, and Huh7." (PMID 38256213, 2024). "scRNA-seq of EGFR-mutated lung cancer patient samples also reveals high BCL2L1 expression, specifically in tumor cells, while MCL1 expression is lower in tumors compared to non-tumor cells." (PMID 39122703, 2024). "Additionally, GX15-070, a pan inhibitor of MCL1, BCL2, BCLXL, BCLW, and BFL1, has been shown to induce cell death in Tregs and enhance clearance of lung cancer cells when combined with a rV/F-CEA-TRICOM vaccine." (PMID 38459020, 2024). "The results showed that miRNA may be involved in the regulation of several lung cancer driver genes, such as BCL2, CYCS, E2F2, MCL1, or MYC, among others." (PMID 38791013, 2024). "The interaction between Mcl-1 and VDAC promotes lung cancer cell migration." (PMID 37714937, 2023). "In addition, miR-29 appeared to increase the rate of apoptosis in leukemia, hepatocellular carcinoma (HCC), gastric cancer, lung cancer, and glioblastoma cases through signaling via BCL-2 or myeloid leukemia cell differentiation protein 1 (MCL-1)." (PMID 34445276, 2021). "We could further demonstrate that NOXA protein mediates the degradation of MCL1 during extended M-arrest and that knockdown of NOXA leads to MCL1 stabilisation and resistance to MTAs in HeLa cervical cancer and A549 lung cancer cells." (PMID 34903710, 2021). "Alternative approaches that induce Mcl1 proteasomal degradation (by GDC-094 treatments, for example), have also been effective in overcoming resistance, thus allowing ABT-737 to have greater effects against BC cells and lung cancer (LC) cells." (PMID 34753495, 2021). "H1299 cells are exactly the lung cancer cells that express high levels of endogenous Mcl-1 but do not express Bcl-2." (PMID 31956373, 2020).
lung carcinoma (continued). "Additional evidence for the attractive role of MCL-1 as a drug target in lung cancer comes from its non-apoptotic involvement in DNA repair." (PMID 33308268, 2020). "As MCL-1 promotes resistance to Cisplatin and because MCL-1 expression relies on RNF113A, we next explored whether RNF113A also contributes to resistance to Cisplatin in lung cancer cells." (PMID 32152280, 2020). "We also provided the evidence of Mcl-1 ubiquitination using immunoprecipitation and analysis of the Mcl-1-ubiquitin complex (Ub-Mcl-1) in the lung cancer cells treated with RT and non-treated control cells." (PMID 31117253, 2019). "Treatment of the lung cancer cells with RT for 4 h dramatically decreased Mcl-1 level, while the addition of MG132 (0–20 μM) could restore the Mcl-1 level." (PMID 31117253, 2019). "Next, we screened alteration of apoptosis-related protein levels by honokiol, and found that honokiol increased DR5 expression and decreased Mcl-1, survivin, and c-FLIP expression in renal carcinoma (Caki, ACHN and A498), lung carcinoma (A549), and cervical cancer (Hela) cells." (PMID 31817770, 2019). "To confirm whether USP13 dictated the stability of MCL1 protein in tumor cells, we introduced two independent siRNAs against USP13 into several lung cancer (SW-1573, NCI-H441 and A549) and ovarian cancer (TOV-21G, HEY and OVCA433) cell lines." (PMID 29335437, 2018). "Although studies have shown that MCL-1 is a target of miR-101 in lung cancer and endometrial cancer cells, the roles of MCL-1 and miR-101 in drug sensitivity have not been identified." (PMID 26036638, 2015). "The E6 antigens of HPV 16 up-regulate interleukin-6 (IL-6) and anti-apoptotic Mcl-1 which, subsequently, may promote the tumor progression of HPV-infected lung cancer." (PMID 23349885, 2013). "In both human and mouse lung cancer cell lines, knocking down HSP90AA1 promoted cell apoptosis through the inhibition of the pro-survival effect of AKT1 by decreasing the phosphorylation of itself and its downstream factors of mTOR and BAD, as well as downregulating Mcl1, Bcl-xl, and Survivin." (PMID 35095481, 2021). "In the same way, not only in a known lung cancer cell line, but we also proved that the absence of Mcl-1 after RT treatment in primary lung cancer cell lines derived from patients could trigger the apoptotic pathway, which led to the death of cancer cells." (PMID 32260280, 2020). "Mcl-1 is the primary anti-apoptosis protein overexpressed in various NSCLC, implying that Mcl-1 inhibition could lead to more successful targeted therapy for lung cancer." (PMID 32069989, 2020). "Furthermore, DYRK1A and Mcl-1 proteins showed co-localization in NSCLC cells and co-expressed in tumor samples from lung cancer patients, revealing that Mcl-1 may be a novel DYRK1A substrate." (PMID 32587776, 2020). "In lung cancer, it has a positive correlation with pathology stage, poor prognosis, and lymph node metastasis, it promotes ovarian cancer progression and chemoresistance to cisplatin and paclitaxel via activating NF‐KB, and it promotes the expression of TWIST1, MCL1(Wu, Huang, Chang, & Chou, 2017)." (PMID 30746900, 2019). "Similarly, IHC assessment of a lung cancer tissue microarray showed that USP13 and MCL1 were upregulated in cancers compared with the matched adjacent normal tissues, and their expression tended to correlate (Spearman’s rank correlation coefficient R = 0.46, P = 0.13)." (PMID 29335437, 2018).
lung carcinoma (continued). "All three variants were detected in primary tumors of two patients (UH1 & UH2), specifically in the DPYD (dihydropyrimidine dehydrogenase), MCL1 (v-myc myelocytomatosis viral oncogene homolog 1, lung carcinoma derived [avian]), and TNK2 (tyrosine kinase, non-receptor, 2) genes." (PMID 25950952, 2015). "To explore the relevance of the signaling pathways we have characterized, in cell lines for clinical patients, the phosphorylation status of Bcl2, Mcl-1, Bad, or Bax in tumor tissues from smoking and nonsmoking lung cancer patients which should be evaluated in future studies." (PMID 24967145, 2014). "LKB1-deficient cell lines with high ΔAUC values exhibited robust apoptosis upon combined inhibition of KRAS/MAPK and MCL-1, while the apoptotic response of LKB1 wild-type (WT) cell lines was minimal, suggesting that LKB1 may modulate apoptotic dependencies of KRAS-mutant lung cancers." (PMID 40316540, 2025). "Here, we report that overexpression of the RUNX2 gene in lung cancer may be related to the inhibition of the intrinsic apoptosis pathway, specifically, through direct transcriptional regulation of the antiapoptotic gene BCL2 and indirect regulation of BCL-XL and MCL1." (PMID 36510562, 2022). "We tested apoptosis proteins such as Mcl‐1, Bax, PUMA and capase‐3 to follow the same trend as that reported in previous studies, and determined that aspirin and aspirin with cisplatin could relieve the apoptosis decrease in lung cancer cisplatin resistant cells." (PMID 32991066, 2020). "Thus, in addition to Bcl2 and Mcl-1, nicotine- or NNK-induced survival may occur, at least in part through inactivation of the BH3-only molecule Bad by phosphorylation, which may contribute to the development of human lung cancer and/or chemoresistance." (PMID 24967145, 2014). "In another word, Mcl-1 is the down-stream target of STAT3, but the canonical JAK is not the up-stream kinase of STAT3 in H1299 lung cancer cells." (PMID 31956373, 2020). "Consistently, western blot analysis of 22 lung cancer and 33 ovarian cancer cell lines revealed that both USP13 and MCL1, but not USP9X, were ubiquitously expressed at the protein level." (PMID 29335437, 2018). "Although it needs to be proven whether these effects can be replicated with established MCL-1 inhibitors, these results demonstrate that the non-apoptotic functions of MCL-1 can be exploited to tackle key vulnerabilities of lung cancer cells." (PMID 33308268, 2020).